ADAMTS5 (ADAM metallopeptidase with thrombospondin type 1 motif 5)
Diseases named in the same sentence as ADAMTS5 in open-access papers (continued):
Sharing a sentence is not in itself a finding about the gene and the disease.
Arthritis (continued). "It is well known that two major proteinases in the ADAMTS family are the capital enzymes contributed in the pathogenesis of arthritis: ADAMTS-4 and ADAMTS-5 called aggrecanase-1 and aggrecanase-2, respectively." (PMID 29137610, 2017). "According to the OA meniscus destabilization model, several researchers found that protecting mice’s joints against degeneration involved active ADAMTS-5 (aggrecanase 2), indicating that the ADAMTS-5-mediated breakdown of aggrecan is critical for the onset of arthritis." (PMID 37259405, 2023). "As a result, the detection of active MMP-3, ADAMTS-5, and TIMP-3 in clinical samples could reveal information regarding the development of arthritis and the response to therapy." (PMID 37259405, 2023). "On the other hand, ADAMTS proteases are also involved in the pathogenesis of acquired and congenital connective tissue disorders, most prominently in arthritis, where ADAMTS4 and ADAMTS5 degrade aggrecan and contribute to the erosion of articular cartilage and joint degeneration." (PMID 34268335, 2021). "Regulation of ADAMTS4 and ADAMTS5 gene expression by pro-inflammatory cytokines is not restricted to arthritis and was also described in the heart and the intervertebral disc." (PMID 34268335, 2021). "Although matrix proteolysis drugs are not yet mainstream, ADAMTS5 blocking is currently examined as a possible treatment in arthritis." (PMID 32917786, 2020). "Although it has yet to be established which aggrecanase is predominant in human arthritis, ADAMTS4 inhibitors still may be beneficial, particularly if they inhibit ADAMTS5 concurrently." (PMID 25606593, 2014). "ADAMTS-5 is of special interest since only lack of the Adamts-5 gene prevents cartilage damage in a mouse model of arthritis." (PMID 24893776, 2014). "Since arthritis is a disease of the entire joint, ADAMTS4 and ADAMTS5 may have variable activity depending on their localization and which cytokines are present to stimulate their gene expression and activation profile." (PMID 25606593, 2014). "TIMP-3 may be a suitable therapeutic treatment for patients with arthritis to suppress not only innate inflammatory cytokines in arthritis but also ADAMTS4 and ADAMTS5." (PMID 25606593, 2014). "ADAMTS5, also known as ADAMTS11, aggrecanase-2 and implantin in mice, is one of the well-studied metalloproteinase in ADAMTS family due to its role as the major aggrecanase in cartilage degradation in arthritis." (PMID 24213506, 2012). "This indicates, according to the authors, that ADAMTS5 may not be the predominant aggrecanase in articular cartilage in the course of arthritis." (PMID 35407621, 2022). "Since both ADAMTS5 and Shh have independent—as well as potential combinatorial—roles during musculoskeletal development, the complex interplay between ADAMTS and Shh could be relevant to the development of musculoskeletal diseases, such as muscular dystrophies and arthritis." (PMID 29518972, 2018). "Roles for Itih1 and Itih2 have not been reported in the valve, but in arthritis, pathological degradation of cartilage has been attributed to ITI-HA complexes serving as substrates for ECM proteases—including ADAMTS-5, which has been described as a key player in myxomatous valve disease." (PMID 37623368, 2023).
breast carcinoma (14 papers, 2011 to 2025). "In this regard, immunostaining of breast cancer tissues samples underlines the close proximity or partial co-localization of Fibulin-2 and ADAMTS-5 in different areas of grade-III invasive ductal carcinomas." (PMID 28099917, 2017). "Little is known about the role of ADAMTS-5 in breast cancer; however, recently, a study suggested that its low expression in this tumor type in women was associated with late-onset tumors (≥55 years)." (PMID 39682243, 2024). "ADAMTS5 has been reported to act as a tumor suppressor gene in breast cancer and hepatocellular carcinoma." (PMID 37238942, 2023). "In fact, fibulin-2 can be degraded by ADAMTS-4 and ADAMTS-5 under the same experimental conditions, which results in an increase of the tumoral properties of breast cancer cells." (PMID 33996918, 2021). "The interaction of ADAMTS-12 with fibulin-2 results in a blockade of the proteolytic degradation of fibulin-2 by ADAMTS4 and ADAMTS-5 and therefore, inhibition of the tumoral properties of breast cancer cells." (PMID 33996918, 2021). "Interestingly, down-regulation of ADAMTS5 was found to be associated with late-onset tumours (≥55 years) compared to ET (≤40 years), (FC = −6.5 in LT and FC = −4.5 in ET, p = 0.013), suggesting the involvement of loss of this gene in the molecular pathogenesis with late-onset breast cancer." (PMID 31292488, 2019). "Further, significant down-regulation of ADAMTS5 in old age patients had been reported for the first time in breast cancer patients." (PMID 31292488, 2019). "QPCR analysis confirmed the up-regulated expression of MMP1, MMP13, and MMP11 genes and down-regulated expression of ADAMTS1 and ADAMTS5 genes in breast cancers observed in the microarray experiments." (PMID 31292488, 2019). "In module 2, mRNA ADAMTS5 was reported to play roles during migration and invasion in breast cancer." (PMID 32010179, 2019). "Our data regarding the cleavage of fibulin-2 by ADAMTS-5 strengthen the tumor-protective role of fibulin-2 in breast cancer." (PMID 31508361, 2019). "While several studies have reported reduced expression of ADAMTS5 in cancers, such as prostate cancer, breast cancer, colorectal cancer, and hepatocellular carcinoma (HCC), others have reported elevated expression of ADAMTS5 in human glioblastomas." (PMID 29891754, 2018). "In special, TIMP-3, a potent inhibitor of ADAMTS-5, has been previously identified in breast cancer samples." (PMID 28099917, 2017). "Presence of Fibulin-2 and ADAMTS-5 was also examined by western blot in a panel of eight paired normal-tumor breast cancer samples with the finding that an immunoreactive band corresponding to the metalloprotease was detected in all tumor samples." (PMID 28099917, 2017). "Then different conditioned media from MCF-7 cells, which showed a low level of endogenous ADAMTS-5 expression among the three breast cancer cell lines employed in this work, were added to normal mammary fibroblasts spheroids embedded in 3D collagen matrix." (PMID 28099917, 2017). "Using in vitro approaches and cultured breast cancer cell lines we demonstrate that Fibulin-2 is a better substrate for ADAMTS-5 than it is for ADAMTS-4." (PMID 28099917, 2017). "In this work we show that the aggrecanases, mainly ADAMTS-5, can cleave Fibulin-2 both in vitro and in cultured breast cancer cell lines." (PMID 28099917, 2017). "There is a number of scientific research for each of the top 10 mRNA genes, well-documenting their significance and association with cancerogenesis: ADAMTS5, TMEM220, ARHGAP20, MICU3; or precisely with breast cancer: COL10A1, MMP11, CAVIN2 (formerly known as SDPR), PLPP3, MME, and CD300LG." (PMID 40724805, 2025). "Thus, it can be inferred that simultaneous presence of Fibulin-2 and ADAMTS-5 can actively modify cellular behavior of breast cancer cells as well as the surrounding mammary fibroblasts, which represent a major and crucial component of tumor stroma." (PMID 28099917, 2017).
breast carcinoma (continued). "We have also investigated the localization of both Fibulin-2 and ADAMTS-5 in breast cancer samples as well as the effect that the conditioned medium of breast cancer cells that exogenously express Fibulin-2 alone or in combination with ADAMTS-5 produces on normal mammary fibroblasts." (PMID 28099917, 2017). "To investigate whether the presence of ADAMTS-12 could affect the behavior of breast cancer cells overexpressing ADAMTS-5, we carried out invasion assays using SK-BR-3 cells bearing in mind their endogenous expression of Fibulin-2." (PMID 28099917, 2017). "In this work we have compared Fibulin-2 digestion pattern generated by MMP-2 with that produced by ADAMTS-5 activity concluding that Fibulin-2 might be a substrate for both metalloproteases in breast cancer." (PMID 28099917, 2017). "To elucidate whether endogenous Fibulin-2 could also be degraded by these proteases, we carried out transfections only with plasmids containing the full-length cDNA for ADAMTS-4 or ADAMTS-5 into SK-BR-3 breast cancer cells, which endogenously express Fibulin-2." (PMID 28099917, 2017). "A strong convergence was also observed for breast cancer: all manuscript-listed genes, including SCARA5, ADAMTS5, MMP11 and CAVIN2, appeared in the outputs of SHAP or LIME." (PMID 40565055, 2025). "The genes namely COL11A1, MMP11 and COL10A1 were found up regulated and PCOLCE2, LAMA2, TMTC1, ADAMTS5, TIMP4 and RSPO3 were found down regulated in breast cancer." (PMID 37238942, 2023). "Among these key genes COL11A1, MMP11 and COL10A1 were highly expressed and PCOLCE2, LAMA2, TMTC1, ADAMTS5, TIMP4, and RSPO3 were having lower expression levels in breast cancer samples." (PMID 37238942, 2023). "In conclusion, our study identified nine key regulators, of which COL11A1, MMP11 and COL10A1 were up regulated and PCOLCE2, LAMA2, TMTC1, ADAMTS5, TIMP4 and RSPO3 were down regulated in breast cancer samples as compared to control samples." (PMID 37238942, 2023). "Similar expression profile of seven among nine genes (except ADAMTS5 and RSPO3) was validated in MCF-7 and MDA-MB-231 human breast cancer cell lines." (PMID 37238942, 2023). "Interestingly, the degradation of fibulin-2 by either ADAMTS-4 or ADAMTS-5 is blocked by the presence of ADAMTS-12 and seems to be a target for the protective role of the fibulin-2/ADAMTS-12 interaction in breast cancer." (PMID 31508361, 2019). "Taking into account previous results showing that ADAMTS-5 induces more significant differences on breast cancer cells behavior than ADAMTS-4, we focused our further efforts on ADAMTS-5 through the examination of the effect of different conditioned media on normal mammary fibroblasts." (PMID 28099917, 2017). "Our data using the poorly invasive breast cancer cell lines MCF-7 and T47D point out that protective role of Fibulin-2 could also be abolished through its degradation by ADAMTS-5." (PMID 28099917, 2017). "miR-451 is downregulated in gastric cancer, breast cancer, and head and neck squamous cell carcinoma, where it executes tumor suppressor functions by targeting macrophage migration inhibitory factors and a disintegrin and metalloproteinase (ADAM) protein family members ADAMTS5 and ADAM10." (PMID 26497997, 2015).
disc degeneration (13 papers, 2009 to 2025). "MMP-13 and ADAMTS-5 have been reported to be involved in the degradation of disc matrix, exacerbating disc degeneration." (PMID 33936382, 2021). "Unlike cartilage, in the nucleus pulposus (NP), both ADAMTS-4 and ADAMTS-5 expressions are elevated in human degenerative disc disease." (PMID 26438479, 2015). "Upregulated genes with known roles in disc degeneration included interleukin-6 (Il-6), matrix metallopeptidase 3 (Mmp3), and a disintegrin and metalloproteinase with thrombospondin motifs 5 (Adamts5)." (PMID 24171898, 2013). "When disc degeneration was assessed by using the Thompson MRI grading score, the grading score was significantly lower (better) in the ADAMTS5 siRNA group than in the control siRNA group (P = 0.02, Mann-Whitney U test)." (PMID 19889209, 2009). "With the rabbit anular puncture model, this study explored the efficacy of a direct injection of ADAMTS5 siRNA into the NP on the delay or attenuation of disc degeneration." (PMID 19889209, 2009). "The intradiscal injection of ADAMTS5 siRNA during the acute phase of disc degeneration after anular puncture in the rabbit delayed the progression of disc degeneration, as assessed by MRI scores, signal intensity of NP on MRI, and histologic scores." (PMID 19889209, 2009). "A single injection of ADAMTS5 siRNA suppressed disc degeneration in the NP, as shown by the significantly improved MRI and histologic grades." (PMID 19889209, 2009). "ADAMTS-5 may be the main enzyme involved in matrix breakdown during the acute phase of puncture injury-induced disc degeneration and septic discitis, whereas in the case of P. acnes infection MMP-3 was predominant." (PMID 35587595, 2022). "In addition, ADAMTS-5 siRNA was shown to retard disc degeneration by directly targeting the protease ADAMTS-5." (PMID 35163637, 2022). "Since metalloproteinases, particularly members of the ADAMTS and matrix metalloproteinase (MMP) families, are major contributors to aggrecan degradation and loss in disc degeneration, MMP-3, ADAMTS-4 and ADAMTS-5 message levels were also examined, as their suppression is essential for disc repair." (PMID 21787415, 2011). "The limited effects of ADAMTS5 siRNA may point to a complex involvement of multiple enzymes in disc degeneration." (PMID 19889209, 2009). "For example, one study demonstrated that leptin promotes catabolic activity in rat NPCs by upregulating the expression of MMP‐1, MMP‐13, ADAMTS4, and ADAMTS5 via activation of the JAK2/STAT3 pathway, suggesting a mechanism contributing to disc degeneration." (PMID 41497807, 2025). "Analyses also showed that Shinbaro 2 administration led to a dose-dependent reduction in disc-degeneration-related factors, such as matrix metalloproteinase (MMP) 9, MMP13, and ADAMTS-5, at the protein and mRNA levels." (PMID 39201178, 2024). "In summary, we have shown evidence that the suppression of ADAMTS5 in turn suppressed IVD degeneration; this suggests the possible contribution of ADAMTS5 to disc degeneration, especially in the NP of the rabbit anular puncture model of disc degeneration." (PMID 19889209, 2009). "Furthermore, they showed differences in overexpression of selective inflammatory and catabolic proteins (p<0.0001) similar to those found in human NP cells of different disc degeneration grades, such as IL-1β, TNF-α, ADAMTS-4, ADAMTS-5 and MMP-3." (PMID 31751427, 2019). "A recent human cadaveric study revealed the presence of aggrecanase-generated aggrecan fragments and abundant levels of ADAMTS5 in human IVDs, regardless of the level of disc degeneration, based on magnetic resonance imaging (MRI) grade classification." (PMID 19889209, 2009).
colorectal cancer (11 papers, 2012 to 2023). A primary or metastatic malignant neoplasm that affects the colon or rectum. "There was one gene consistently identified as one of the genes with most significantly different mutation rates between prognostic (sub)groups, ADAMTS5, whose expression was reported to be correlated with the invasiveness or patient survival of lung and colorectal cancers." (PMID 30902072, 2019). "Abnormal expression of Adamts5 is an effective marker of lymphatic invasion and lymph node metastasis in colorectal cancer." (PMID 36902425, 2023). "A recent report indicated that high ADAMTS5 expression in colorectal cancer patients correlated with higher levels of lymphatic invasion and lymph node metastasis." (PMID 29891754, 2018). "Furthermore, in the context of colorectal cancer, heightened expression of ADAMTS5 has emerged as a significant indicator of lymphatic infiltration and metastasis." (PMID 37502362, 2023). "ADAMTS5 was targeted by miR-140-5p to suppress the metastasis in colorectal cancer." (PMID 34140036, 2021). "Besides, two other studies have shown that the upregulation of ADAMTS5 promotes progression in colorectal cancer and drives metastasis in colon and non-small cell lung cancer." (PMID 32010179, 2019). "Our findings support the notion that overexpression of ADAMTS-4 and ADAMTS-5 in colorectal cancer might be a possible invasive mechanism of cancer cells in order to degrade proteoglycans of ECM." (PMID 25786261, 2015). "Top statistically significant hits included ADAMTS5, ATP6V1C2, and S100A6—genes that have been previously identified as biomarkers for colorectal cancer." (PMID 37138315, 2023). "ADAMTS1 shows high frequency promoter methylation in lung and pancreatic cancers; ADAMTS5 and ADAMTS1 also show high frequency methylation in colorectal cancer." (PMID 34603444, 2021). "We inferred that other published miR-140 targets, such as ADAMTS5 and IGFBP5 in colorectal cancer, Pin1 in liver cancer, and IGF2BP1 in cervical cancer, which are associated with tumor migration and invasion, may contribute to these GC cell phenotypes." (PMID 28818100, 2017).
atherosclerosis (9 papers, 2016 to 2025). A disease characterized by the build-up of fatty material and calcium deposition in the arterial wall resulting in partial or complete occlusion of the arterial lumen. "In addition, decreased ADAMTS-5 expression was found in atherosclerosis of apolipoprotein E (ApoE) null mice, associated with the accumulation of aggrecan and versican." (PMID 31929842, 2019). "ADAMTS5 is considered to have a protective effect on atherosclerosis by regulating the catabolism of vascular proteoglycan and improving the deposition of lipoprotein." (PMID 37234367, 2023). "A few studies have illustrated aberrant regulation of ADAMTS-5 in vascular diseases, including atherosclerosis, cerebral cavernous malformation, calcific aortic valve disease (CAVD), and aortic dilatation." (PMID 33934089, 2021). "Our group highlighted the importance of ADAMTS‐5 in a mouse model of atherosclerosis 44: lower levels of ADAMTS‐5 accompanied accumulation of versican in aortas of apolipoprotein (apo)E‐knockout mice." (PMID 26940365, 2016). "Taken together, these data suggest that the proteolytic activity of ADAMTS-5 is essential in regulating the levels of cardiovascular PGs and that disturbances could affect the disease process in atherosclerosis and TAAD." (PMID 33352066, 2020). "Such an antibody may be used to rescue ADAMTS-5 proteoglycanase activity in mouse models of atherosclerosis and TAAD." (PMID 33352066, 2020). "Meanwhile, ADAMTS-5 concentrations were a significant predictor of multiple atherosclerotic involvement (CAD+PAD) and had good diagnostic performances to discriminate multiple manifestations of atherosclerosis." (PMID 31929842, 2019).
hepatocellular carcinoma (8 papers, 2018 to 2025). A malignant tumor that arises from hepatocytes. "Variants of ADAMTS14 and ADAMTS5 were associated with susceptibility to hepatocellular carcinoma in a Chinese Han population, however the functional effects of these polymorphisms that occur near the anti-angiogenic TSR domain were not demonstrated." (PMID 33805340, 2021). "Notably, high ADAMTS5 expression in hepatocellular carcinoma has been associated with a poor prognosis." (PMID 39575481, 2025). "In this study, we constructed a scoring model (VM Score) associated with VM, which included three risk factors, SPP1, ADAMTS5, and ZBP1, revealing potential prognostic biomarkers for hepatocellular carcinoma." (PMID 39748947, 2024). "In hepatocellular carcinoma, only ADAMTS5 was suggested to inhibit angiogenesis through down-regulation of VEGF in HCC cells." (PMID 33805340, 2021).